WASHC3 (WASH complex subunit 3)
Description:
Acts as a component of the WASH core complex that functions as a nucleation-promoting factor (NPF) at the surface of endosomes, where it recruits and activates the Arp2/3 complex to induce actin polymerization, playing a key role in the fission of tubules that serve as transport intermediates during endosome sorting.
Synonyms: CCDC53; CGI-116
Tractability: PROTAC: ubiquitination databases record sites on it.
Gene: Protein-coding gene on chromosome 12 (102,011,769 to 102,062,149, reverse strand). Ensembl gene ENSG00000120860.
Subcellular location: Early endosome
Subcellular location (Human Protein Atlas): Vesicles
Gene Ontology:
Molecular function: protein binding
Biological process: actin filament polymerization; endosomal transport; exocytosis; regulation of Arp2/3 complex-mediated actin nucleation
Cellular component: WASH complex; early endosome membrane; early endosome
Genetic constraint (gnomAD): Loss-of-function variants: 3 observed, 4.44 expected, observed/expected ratio (o/e) 0.68, 90% interval 0.3 to 1.62. That is too few expected variants to judge how well the gene tolerates losing a copy. Missense variants: 56 observed, 51.93 expected, observed/expected ratio (o/e) 1.08, 90% interval 0.87 to 1.35. Synonymous variants: 25 observed, 19.3 expected, observed/expected ratio (o/e) 1.3, 90% interval 0.94 to 1.77.
Homologues: Orthologues: macaque WASHC3 (94% identical), mouse Washc3 (90% identical), pig WASHC3 (90% identical), dog WASHC3 (88% identical), chimpanzee WASHC3 (87% identical), rabbit WASHC3 (85% identical), rat Washc3 (85% identical), guinea pig WASHC3 (82% identical), tropical clawed frog washc3 (74% identical), zebrafish washc3 (64% identical), Drosophila melanogaster CCDC53 (32% identical), Caenorhabditis elegans ddl-1 (27% identical).
Diseases named in the same sentence as WASHC3 in open-access papers:
WASHC3 is named in the same sentence as 3 diseases in open-access papers, as found by Europe PMC text mining. Sharing a sentence is not in itself a finding about the gene and the disease. The quoted sentences say what the papers report.
Hypertension (1 paper, 2025). The presence of chronic increased pressure in the systemic arterial system. "WASHC3 regulates endolysosomal membrane trafficking, and how the gene may contribute to hypertension mandates further research." (PMID 39663699, 2025).
WASHC3 also shares sentences with these, for which no sentence is quoted: prostate carcinoma (1 paper); schizophrenia (1).